GDF15 (growth differentiation factor 15)
Diseases named in the same sentence as GDF15 in open-access papers (continued):
Sharing a sentence is not in itself a finding about the gene and the disease.
Sepsis (continued). "This study aims to compare the temporal changes in GDF15 levels with those of classical inflammatory biomarkers, such as CRP, PCT, and P-SEP, in septic patients, exploring its potential role as a biomarker for clinical monitoring in sepsis." (PMID 40941711, 2025). "Other biomarkers, such as urinary chitinase-3-like protein 1 (u-CHI3L1) for early detection of (sepsis-induced) acute kidney injury (AKI), and plasma growth differentiation factor-15 (GDF15) for abdominal sepsis, are also typically used, along with various others." (PMID 40681771, 2025). "Serum GDF-15 levels have been found to be elevated in sepsis, regardless of the pathogen involved, and have been correlated with prognosis, severity, and survival, as well as being elevated in SARS-CoV-2 in adults and children." (PMID 39000420, 2024). "We observed strong correlations of plasma GDF15 levels with the levels of C-reactive protein (CRP), procalcitonin (PCT), lactate dehydrogenase (LDH), and lactate as well as Sequential Organ Failure Assessment (SOFA) scores in patients with sepsis." (PMID 38725041, 2024). "GDF15 regulates the polarization of macrophages to M2 by activating the PI3K/Akt signaling pathway, reduces the level of M1 in macrophages, and has a protective effect on the survival rate of sepsis mice model." (PMID 37691951, 2023). "ROC curve analysis of GDF15 combined with inflammatory markers and SOFA in the diagnosis of sepsis." (PMID 34566964, 2021). "In wild-type and GDF-15 overexpressing mice, GDF-15 protected both cardiac and renal tissues from excessive inflammation, with LPS-induced sepsis not affecting the organs." (PMID 32508832, 2020). "We measured GDF-15 levels in 219 critically ill patients (146 with sepsis, 73 without sepsis) upon admission to the intensive care unit (ICU), in comparison to 66 healthy controls." (PMID 29180833, 2017). "Unlike classical biomarkers, GDF15 reflects the organism’s adaptive response to systemic inflammation, tissue injury, and metabolic stress, suggesting its utility as a complementary biomarker in sepsis." (PMID 40941711, 2025). "However, among the patients with sepsis, plasma IL-6 levels of the non-survivors were significantly higher than those of the survivors from day 1 to days 6-8, as were those of GDF-15 on days 2-3 and 6-8." (PMID 35095877, 2021). "Strikingly, patients that survived ICU treatment showed significant lower serum levels of GDF-15 than nonsurvivors (median 5028 versus 9505 pg/mL; p < 0.001) in all patients as well as in the subgroup of sepsis patients (median 6244 pg/mL versus 9964 pg/mL; p = 0.01)." (PMID 29180833, 2017). "The significant decline in GDF15 levels over the 10-day follow-up and its meaningful correlations with CRP and renal dysfunction indicators such as BUN, creatinine, and eGFR suggest that this biomarker may reflect not only the inflammatory response but also organ damage in sepsis." (PMID 40941711, 2025).
acute coronary syndrome (50 papers, 2010 to 2026). Signs and symptoms related to acute ischemia of the myocardium secondary to coronary artery disease. "GDF-15 measurement is used clinically for risk stratification of clinical outcomes in patients with acute coronary syndrome (ACS) and chronic HF and assessment of bleeding risk in patients with AF in Western countries." (PMID 37396418, 2023). "It has been reported in clinical studies that circulating levels of GDF15 were increased in patients with an acute coronary syndrome, Moreover, patients with elevated levels of GDF15 (>1800 ng/L) had a high risk of death within one year." (PMID 34445593, 2021). "Lindholm had reported a study included 17 095 patients with acute coronary syndrome, GDF-15 was the strongest marker associated with all-cause death." (PMID 32746821, 2020). "A weak association between GDF-15 and lysis time observed in univariate analysis has been recently reported in patients after acute coronary syndrome (ACS) included in the PLATelet inhibition and patient Outcomes (PLATO) trial." (PMID 31280356, 2020). "Serum GDF-15 concentrations have been shown to be also associated with the risk of acute coronary syndrome as well as its prognosis." (PMID 24484525, 2014). "Moreover, high GDF-15 levels are associated with an increased risk of developing adverse left ventricular reshaping and HF following an episode of acute coronary syndrome (ACS)." (PMID 37298029, 2023). "Hence, the study aimed to understand the association between serum tenascin-C, GDF-15 levels and risk of the acute coronary syndrome among T2DM patients." (PMID 33312062, 2020). "Increased levels of GDF-15 have been established as a predictive factor for several cardiovascular diseases, including CAD, acute coronary syndromes (ACS), and chronic heart failure, as well as for all-cause cardiovascular mortality." (PMID 39330316, 2024). "Ethnic differences in GDF15 have been reported in acute coronary syndrome, with median GDF15 concentrations in the range of 1244–1835 ng/dl in Europeans and 650 ng/dl in Asians." (PMID 35510313, 2022). "Several studies have investigated the prognostic value of GDF15 in acute coronary syndrome (ACS) and other heart diseases." (PMID 34445593, 2021). "Wang Y, Zhen C, Wang R, Wang G. Growth-differentiation factor-15 predicts adverse cardiac events in patients with acute coronary syndrome: A meta-analysis." (PMID 33566936, 2021). "In the past decade, accumulating evidence has demonstrated that the GDF-15 serve as a potential prognostic factor in patients in with acute coronary syndrome." (PMID 32746821, 2020). "Accordingly, circulating levels of GDF-15 are characteristically elevated in patients with neoplastic disease, heart failure, and acute coronary syndrome." (PMID 29714603, 2018). "Current ongoing clinical trials are needed to further clarify the benefits of GDF-15 in predicting the prognoses of patients with acute coronary syndrome." (PMID 27154403, 2016). "Serum levels of GDF-15 levels rise modestly in acute coronary syndrome and congestive heart failure, in both conditions accurately predicting one-year mortality, but are very elevated in acute pulmonary embolus and pulmonary hypertension." (PMID 26243260, 2015). "GDF-15 has been extensively studied as a biomarker for cardiovascular disease and was initially described as a marker of poor outcomes in acute coronary syndromes and chronic left-sided heart failure." (PMID 23706007, 2013). "Growth differentiation factor-15 and high-sensitivity C-reactive protein predict death following an acute coronary syndrome." (PMID 20529285, 2010). "GDF15 was also reported as prognostic biomarker in patients with acute coronary syndrome." (PMID 41303556, 2025). "However, as noticed both in the present study and in previous studies, GDF‐15 concentrations remain fairly constant from the acute to stable phase after acute coronary syndrome, in contrast to hs‐CRP, cardiac troponin, and natriuretic peptides." (PMID 36565198, 2023).
acute coronary syndrome (continued). "Studies showed that circulating levels of GDF-15 are increased in patients with cardiovascular diseases, namely with chronic HF and acute coronary syndrome, proving GDF-15 levels provide prognostic information and function as a biomarker of risk of death in these patients." (PMID 35911521, 2022). "Moreover, the circulating concentration of FSTL1 has been shown to be dependently related to GDF15 and act as a biomarker to predict cardiovascular mortality in patients with acute coronary syndrome." (PMID 32210839, 2020). "Frailty was found to be associated with GDF15, independent of age, in older adults who had recovered from acute coronary syndrome." (PMID 32310257, 2020). "Recent studies have shown Growth differentiation factor–15 (GDF-15) that is a member of the transforming growth factor β (TGF-β) superfamily might be a potential predictive cytokine for the prognosis of Acute coronary syndrome (ACS)." (PMID 27154403, 2016). "Recent findings also suggested that the secreted protein FSTL-1 could be an upstream inducer of GDF15 production and an independent prognostic biomarker in acute coronary syndromes." (PMID 25171167, 2014). "Although many of the effects of GDF-15 remain unknown, recent work has begun to elucidate its role in acute coronary syndromes." (PMID 23706007, 2013). "The association of GDF15 with early EPC function is novel and warrants further investigations in particular based on the accumulating evidence of GDF15 as a cardiovascular biomarker predicting cardiovascular adverse events in patients with acute coronary syndromes." (PMID 21858032, 2011). "But the level of GDF-15 measured, after 36 months, was a significant predictor of MACE in acute coronary syndrome patients." (PMID 26075263, 2015). "GDF-15 is a member of the TGF-β cytokine superfamily that is produced in response to oxidative stress, inflammation, and injury and is an emerging marker in acute coronary syndromes and HF." (PMID 34658887, 2021). "T2DM patients with higher serum GDF-15 and TNC levels were at higher risk of acute coronary syndrome independent of other cardiovascular risk factors." (PMID 33312062, 2020). "GDF-15 has been recognized as a biomarker of mortality and cardiovascular events in patients with ST-elevation or non-ST-elevation acute coronary syndromes." (PMID 31258506, 2019). "Circulating GDF-15 remains relatively stable after acute coronary syndromes without signs of HF, compared to other biomarkers such as cardiac troponin or hs-CRP showing a curve-shaped course, suggesting that GDF-15 reflects chronic disease burden." (PMID 31252588, 2019). "Interestingly, after a month of an acute chest pain, GDF-15 was also described as a prognostic marker for non-ST elevation acute coronary syndrome." (PMID 38398274, 2024).
pancreatic cancer (48 papers, 2008 to 2025). "Pancreatic cancer has a significantly increased ability to secrete GDF-15, and high levels of GDF-15 are strongly associated with the poor prognosis and survival of pancreatic cancer patients." (PMID 38335385, 2024). "While assessing for an inflammatory marker, MIC-1/GDF-15 levels were found to be elevated and significantly associated with cardiovascular diseases, cardiomyopathies, and pancreatic cancer in multiple studies." (PMID 37623681, 2023). "To investigate GDF-15 expression in plasma of pancreatic cancer patients, we first performed Enzyme-Linked Immunosorbent Assays (ELISAs) to evaluate GDF-15 expression in 20 normal plasma and 34 pancreatic cancer plasma." (PMID 33201838, 2020). "While GDF15 has been linked to platinum resistance in pancreatic cancer and ovarian cancer, it has also been shown to be a common platinum-responsive gene, and was identified as a potential serum marker for cisplatin-response of ovarian cancer cells." (PMID 27184254, 2016). "An anti-GDF15 monoclonal antibody, ponsegromab, was recently shown to ameliorate cachexia caused by non-small cell lung cancer and pancreatic cancer 62, and CLIA-certified assays exist for measuring PTHrP and GDF15 in plasma." (PMID 40964365, 2025). "Pancreatic cancer cells adopted a more aggressive metastatic phenotype through the upregulation of Growth Differentiation Factor 15 (GDF15)." (PMID 40371393, 2025). "Growth differentiation factor-15 (GDF-15) is expected to be a novel biomarker for the diagnosis, efficacy prediction, and prognosis assessment of pancreatic cancer patients." (PMID 38335385, 2024). "This property of MIC-1/GDF-15 and its role in mediating inflammation can serve as an important connecting link between coronary atherosclerosis and pancreatic cancer." (PMID 37623681, 2023). "Transcription of GDF15 is regulated by the cAMP response element binding protein 1 (CREB1) in a human pancreatic cancer cell line, making cAMP a likely second messenger also for exercise-induced GDF15 production in the liver." (PMID 36545337, 2022). "Taken together, these results suggest that BRD4 upregulates GDF15 by inducing NR5A2 expression in pancreatic cancer cells." (PMID 33850096, 2021). "Stress responses involving the Akt pathway can become dominant in cases with pancreatic cancer complicated by high levels of circulating GDF-15, providing biological validation for a cut-off for serum GDF-15 in pancreatic cancer." (PMID 34638326, 2021). "Kalli and colleagues studied pancreatic cancer and found that GDF-15 expression was upregulated in the metastatic process through the Akt/CREB1 pathway." (PMID 34070192, 2021). "Western blot and RT-qPCR showed that the mRNA and protein levels of GDF15 were significantly increased in NR5A2 overexpressed pancreatic cancer cells." (PMID 33850096, 2021). "In pancreatic cancer, solid stress can either activate fibroblasts or directly act on pancreatic cancer cells to promote migration via the GDF15-Akt pathway." (PMID 33922795, 2021). "Overall, our study suggests that BRD4/NR5A2/GDF15 axis is a promising therapeutic target in pancreatic cancer." (PMID 33850096, 2021). "Conversely, recent evidence from in vitro and in vivo pancreatic cancer models suggests that NF‐κB regulates GDF‐15, which in turn signals macrophages to suppress their proapoptotic activity thereby stimulating early cancer development." (PMID 33784024, 2021). "In our study, we found that GDF15 was transcriptionally induced by NR5A2 and that GDF15 overexpression promoted pancreatic cancer cell proliferation and invasion." (PMID 33850096, 2021). "GDF15 silencing significantly inhibited the proliferation and invasion ability of pancreatic cancer cells, whereas GDF15 overexpression remarkably enhanced pancreatic cancer cell proliferation and invasion." (PMID 33850096, 2021).
pancreatic cancer (continued). "Solid stress increased GDF-15 expression by transcriptionally regulating GDF-15 expression through activation of the Akt pathway in pancreatic cancer cells." (PMID 34638326, 2021). "Next, we showed that NR5A2 enhanced the malignancy of pancreatic cancer cells by inducing the transcription of GDF15." (PMID 33850096, 2021). "In common cancers, including breast, colon, prostate, and pancreas cancers, GDF-15 is produced in tumor tissues." (PMID 34150865, 2021). "More importantly, we demonstrated that NR5A2 promoted pancreatic cancer progression by upregulating GDF15 expression in vitro and in vivo." (PMID 33850096, 2021). "Subsequently, according to the reports, different concentrations of recombinant human GDF-15 protein, 0ng/ml, 5ng/ml, 10ng/ml, 20ng/ml, and 40ng/ml, were chose to culture with the pancreatic cancer cell lines AsPC-1, BxPC-3, Panc-1 and Hs766t." (PMID 33201838, 2020). "We also performed immunohistochemistry (IHC) assays to detect GDF-15 expression in pancreatic cancer tissues." (PMID 33201838, 2020). "In this study, we first discovered that GDF-15 is overexpressed in pancreatic cancer blood and tissues and that this high expression of GDF-15 is positively correlated with a poor survival of PDAC patients." (PMID 33201838, 2020). "To illuminate the biological function of GDF-15 in pancreatic cancer, we first detected GDF-15 expression in normal pancreatic epithelial cell line (HPDE) and four pancreatic cancer cell lines, AsPC-1, BxPC-3, Panc-1 and Hs766t." (PMID 33201838, 2020). "Knockdown experiments in pancreatic cancer cells showed GDF-15 to be an effector of Twist-mediated changes, including enhanced invasion and chemoresistance." (PMID 32508832, 2020). "The results indicated that GDF-15 expression was significantly elevated in pancreatic cancer blood compared with that in normal samples." (PMID 33201838, 2020). "At the same time, compared with the normal pancreatic epithelial cell line HPDE, GDF-15 expression was upregulated in pancreatic cancer cell lines, AsPC-1 and BxPC-3." (PMID 33201838, 2020). "Depletion of tumor-derived GDF-15 in an orthotopic pancreatic cancer model and in Ras-driven tumor xenografts hence restored the immune surveillance function of tumor-infiltrating macrophages, resulting in improved tumor control." (PMID 32508832, 2020). "Consistently, compared with 7 normal pancreatic tissues, GDF-15 was upregulated in 21 pancreatic cancer tissues." (PMID 33201838, 2020). "Because of the different phenotype and genotype of pancreatic cancer cell lines, GDF-15 expression was different between the various cancer cell lines." (PMID 33201838, 2020). "In this study, we found that PDAC cells can auto secrete GDF-15 protein, which was upregulated in pancreatic cancer tissues and blood samples compared with normal human pancreas and plasma." (PMID 33201838, 2020). "Overall, these results suggest that the tumor-promoting effects of GDF-15 in pancreatic cancer are mediated by the GDF-15/GFRAL pathway." (PMID 33201838, 2020). "GDF15 secretion by tumor cells generates an immune suppressive environment that accelerates the development of pancreatic cancers in animal models." (PMID 32046099, 2020). "This was consistent with the effect of GDF15 on the migration of osteosarcoma and pancreatic cancer cells." (PMID 33098235, 2020). "Another study based on pancreatic cancer models indicated that tumor cells use GDF-15 during the early stages of tumorigenesis to evade macrophage-mediated immune surveillance." (PMID 32508832, 2020). "Our findings, together with previous evidence, indicate that GDF-15/GFRAL axis can promote pancreatic cancer proliferation and migration." (PMID 33201838, 2020). "Cell proliferation assays showed that GFRAL overexpression significantly enhanced pancreatic cancer cell proliferation after coculture with 0ng/ml, 10ng/ml or 20ng/ml GDF-15 protein." (PMID 33201838, 2020).